CD4 (CD4 molecule)
Diseases named in the same sentence as CD4 in open-access papers (continued):
Sharing a sentence is not in itself a finding about the gene and the disease.
autoimmune disease (continued). "In a recent study, CR in fact attenuated experimental autoimmune encephalomyelitis (EAE, a rodent model for multiple sclerosis) in mice, an autoimmune disease driven by antigen-specific Th1 and Th17 response and mitigated by Treg cells; however, CD4+ T cell subsets were not examined in that study." (PMID 23531279, 2013). "Indeed, mice deficient in JAK3 or STAT5A/B develop a severe immunodeficiency that is followed by multiple organ autoimmune diseases, a decreased number or the absence of CD4+CD25+ nTreg in their peripheral lymphoid organs, and early death." (PMID 21647403, 2011). "Our results, showing that IL-2 immune complex can promote the breakdown of peripheral tolerance by memory-like CD8+ T cells in the absence of CD4+ T cells help, have important implications for the development of therapies for autoimmune diseases as well as cancer immunotherapies." (PMID 20856822, 2010). "The identification of CD4+CD25+ regulatory T cells (Tregs) as a crucial component of self-tolerance has opened a major area of investigation and numerous studies have demonstrated the potent influence of Tregs in suppressing autoimmune disease, transplantation and graft-versus-host disease." (PMID 19543397, 2009). "Largely intact ex vivo cytokine secretion in peripheral CD4+ naïve and memory T cells from patients with STAT3 GOF Syndrome presented here may also support the notion of tissue-specific disease pathogenesis versus broad systemic autoinflammatory/autoimmune disease." (PMID 39836489, 2025). "However, the role of APOO in CD4+ T cells and autoimmune diseases has not been previously reported." (PMID 41244589, 2025). "MRG-001 given at the mid-dose dramatically increased circulating CD4+Foxp3+ and CD8+Foxp3+ Tregs suggesting its immunomodulatory properties and that MRG-001 could be used as an immunoregulatory therapy in a variety of human diseases including autoimmune diseases and transplant rejection." (PMID 37633275, 2023). "Human and mouse CD4+FoxP3+ T cells (Tregs) comprise non-redundant regulatory compartments which maintain self-tolerance and have been found to be of potential therapeutic usefulness in autoimmune disorders and transplants including allogeneic hematopoietic stem cell transplantation (allo-HSCT)." (PMID 35799783, 2022). "It is known that these CD4+CD28null T lymphocytes are expanded in some situations not only as an immunosenescence process but also under other clinical conditions involving chronic activation of the immune system, such as viral infections or autoimmune diseases." (PMID 34202487, 2021). "In addition, CD4+ Tscm may involve in graft-versus-host disease (GVHD) and autoimmune disease." (PMID 34527440, 2021). "Therefore, the abnormal disease-specific expression level of MBD4 in SLE CD4+ T cells may have unique effects on immune activation, which causes deterioration into a systemic disease in SLE rather than an organ-specific autoimmune disease." (PMID 29018507, 2017). "Furthermore, similar regulatory CD4+ IELs are present in WT mice and another TCR-transgenic (KBx/N) mouse strain, indicating that autoreactive CD4+ IELs that cross-react with intestinal antigens could be pivotal in the prevention of autoimmune diseases." (PMID 27198196, 2016). "Although the incidence of autoimmune diseases in patients with chronic hepatitis B was not investigated in this research, it could be presumed that the autoimmune manifestations might be associated with the augmented function of blood CXCR5+CD4+ T cells." (PMID 27612199, 2016). "Therefore, CD4+CD25+ T cells play an important role in maintaining the stability of the internal environment, while the decrease or dysfunction of Treg may result in autoimmune diseases." (PMID 25548591, 2014).
autoimmune disease (continued). "The biological impact that soluble MICA and MICB might exert on the particular subset of CD4+NKG2D+ T cells is not well understood, but it has been proposed that pro-inflammatory cytokines may neutralize the NKG2D down-regulation induced by soluble MIC molecules in patients with autoimmune disease." (PMID 23947399, 2013). "Therefore, the suppressive characteristics of CD4+CD25+ regulatory T cells have made them an attractive candidate for immunotherapy, and numerous studies using animal models have demonstrated their potential for the control of autoimmune diseases as well as transplant rejection and GVHD." (PMID 17284325, 2007). "In the context of autoimmune disease, the role of TYK2 in CD4+ T cells, but not CD8+ T cells, has been well described." (PMID 38351043, 2024). "Similar enrichment patterns, such as Treg Naive in most autoimmune diseases and Tnaive MX1 in SLE, were observed, while caution should be taken as marker gene detection is not optimal for CD4+ T cells as in the previous section." (PMID 38359792, 2024). "In individuals with autoimmune disease, CD8 Treg do not productively engage and eliminate autoreactive CD4 T cells." (PMID 39559361, 2024). "In VDR-knockout mice (VDR-KO), VDR has been shown to be non-essential for the development of CD4+, CD8+, and CD4+ FOXP3+ T-cells, though its absence contributes to the development of autoimmune diseases." (PMID 37764988, 2023). "CD4 T cells play a major role in the pathogenesis of autoimmune diseases, and the function of CD96 in CD4 T cells has not yet been reported." (PMID 35769669, 2022). "There was no statistical difference in CD3+, CD8+, CD4+CD25highCD127low T, CD19, CD19hiCD21loCD38lo, and follicular T helper cell counts in CVID patients with or without autoimmune disorders." (PMID 34290696, 2021). "Serum immunoglobulin concentrations and CD3+, CD8+, CD4+CD25highCD127low, CD19, CD19hiCD21loCD38lo and follicular T helper cell counts were compared between CVID patients with and without autoimmune disorders." (PMID 34290696, 2021). "Since MSC immunomodulation has been best demonstrated toward CD4 cells, it is no surprise that clinical trials of MSCT for autoimmune diseases collectively are the most numerous." (PMID 34008922, 2021). "There was no statistical difference in CD3+, CD8+, CD4+CD25highCD127low T reg, CD19, CD19hiCD21loCD38lo, and follicular T helper cells in CVID patients with or without autoimmune disorders." (PMID 34290696, 2021). "On the contrary, the number of CD4+ and CD8+ T cells in many autoimmune diseases has no change, but actually the function of them is very high, which eventually leads to a hyper-state of adaptive immunity." (PMID 31857499, 2019). "Functionally, some studies showed that CD4+CD25−FoxP3+T cells have no inhibitory function; others indicated that these cells can inhibit inflammation in immune rejection and autoimmune diseases." (PMID 30050955, 2018). "In addition, EI-03 was also showed to inhibit IFNγ production both in CD4+ T cells and in CD8+ T cells, implying that EI-03 may exhibit a more broad effect in controlling the function of DCs and the differentiation of T cell subsets for treatment of T cell-mediated autoimmune diseases." (PMID 25962726, 2015). "CD4+CD25+ Treg cells can play a critical role in the prevention of autoimmunity, as evidenced by the cataclysmic autoimmune disease that develops in mice and humans lacking the key transcription factor Foxp3." (PMID 23133752, 2012). "Studies with Faslpr mice lacking MHC class I, MHC class II, CD4, or CD8 suggested that CD8+ T cells and the derivative DN cells are not essential for autoimmune disease development, whereas CD4+ T cells are required." (PMID 22102903, 2011). "However, autoimmune CD4+ TRM are not as well studied, and many critical questions remain as to their potential contribution to autoimmune disease pathology." (PMID 32106536, 2020).
autoimmune disease (continued). "The immune alteration (depending on the CD4 and CD8 count) may lead to the development of autoimmune diseases, although this is not a frequent event." (PMID 31684052, 2019). "Unlike CD4+CD25+Foxp3+ Tregs, which dominate hematological system tumors and autoimmune diseases, γδ T cells play a key role in the pathological progress of AMI and it may be associated with the IL-17A mediated pathway, but the specific mechanism is unknown." (PMID 29976209, 2018). "Additionally, the absence of CD4+CD25+ Treg cells can lead to organ-specific and non-specific autoimmune disease such as gastritis, thyroiditis and systemic lupus erythromatosis, while application of these cells can prevent or delay these diseases." (PMID 29706856, 2018). "The vast majority of studies investigating the presence and role of CD4+CD28− T cells in CVD and autoimmune diseases did so without considering participant CMV infection status, suggesting that many researchers are unaware of the association of an expansion of this subset with CMV infection." (PMID 28303136, 2017). "Moreover, mainly in this latter condition, a non-negligible number of CD4+ cells also expressed the CD8 molecule, as already found in intestinal mucosa and several autoimmune diseases; as a result, the sum of these two subsets exceeded 100 %." (PMID 26206376, 2015). "Furthermore patients with autoimmune disease had significant lower absolute numbers of CD3, CD4 and CD8 positive T cells compared to patients without complications." (PMID 22526591, 2012). "While total inhibition of CD4+ T helper cells is not optimal for the development of therapeutics, our data sheds light on the utility of developing therapeutics with less activity at LXR while retaining ROR activity for the treatment of autoimmune diseases." (PMID 23029557, 2012). "Indeed, mice deficient in IL-2, IL-2R, JAK-3, or STAT5A/B have an absent or reduced number of thymic and peripheral CD4+ CD25+ nTreg and consequently develop multiple organ autoimmune diseases." (PMID 21647403, 2011). "Importantly, we found no increase in the frequency of CD4 T cells able to produce IL-17 in CVID patients presenting with autoimmune disease, either with autoimmune cytopenia or other autoimmune disorders." (PMID 21826211, 2011). "Therefore, in the absence of CD4+ T lymphocyte infusion after thymectomy in BALB/c mice, the reduction of autoimmune-preventive CD25+ T cells leads to the development of autoimmune gastritis and the emergence of various organ-specific autoimmune diseases." (PMID 36244973, 2022).
tuberculosis (1,221 papers, 2005 to 2026). A chronic, recurrent infection caused by the bacterium Mycobacterium tuberculosis. "Deficiency of CD4+ T cells increases the risk of TB and can transform an infection into active tuberculosis." (PMID 41684947, 2026). "South African treatment guidelines rely on CD4 count to guide prophylactic and diagnostic steps, such as reflex testing for opportunistic infections like cryptococcosis or tuberculosis." (PMID 40986527, 2025). "This immunity depends on CD4+ T cells as evidenced by the fact that people and primates with CD4+ T cell deficiency due to immunodeficiency virus infection, and mice genetically deficient or depleted of CD4+ T cells, are hyper-susceptible to tuberculosis." (PMID 40489538, 2025). "Its high expression in tuberculosis patients, particularly in CD4+ T cells with a CTL phenotype, is associated with increased production of perforin and granzymes, further enhancing the cytolytic activity against Mtb." (PMID 40825006, 2025). "For HIV-uninfected patients, older age and previous tuberculosis were additional risk factors, while lower weight and CD4 cell count were significant for HIV-infected patients." (PMID 40275342, 2025). "The use of a point of care urine lipoarabinomannan LFA to assist in the diagnosis of active tuberculosis is recommended by the WHO for HIV-positive individuals with risk factors including low CD4+ T cell counts." (PMID 40198673, 2025). "CCR6+ CD4 T cells were recently implicated in the prevention of tuberculosis-associated immune reconstitution syndrome, and their detection only in young animals aligns with better disease resolution in this group." (PMID 38771046, 2024). "The risk of new infection of tuberculosis was 2.22 times among HIV-positive children on ART whose CD4 count below the threshold (<200 cells/mm3) than children who had greater (≥200 cells/mm3)." (PMID 38968268, 2024). "Patients who were not suffering from tuberculosis were 1.33 times at risk of dying before reaching a CD4 count of more than 500 cells/mm3 [aSHR 1.33; 95% CI (0.96–1.85)] compared to the prevalent tuberculosis patients." (PMID 39058196, 2024). "HIV-induced progressive CD4 depletion is associated with an increased risk of tuberculosis (TB), disseminated TB, and death." (PMID 38595896, 2024). "Infection with Mycobacterium tuberculosis (Mtb) in people with HIV (PWH) is associated with depletion of Mtb-specific CD4 T cell responses, increased risk of progression to active tuberculosis (TB) disease, and increased immune activation." (PMID 38366732, 2024). "The essential role of MHC-II-restricted CD4+ T cells in mounting a defense against tuberculosis becomes evident in individuals with HIV-related CD4+ T cell impairments, who exhibit a higher susceptibility to the disease." (PMID 39108269, 2024). "In humans, L. loa has been associated with impaired CD4+ memory T cell responses to tuberculosis antigen, suggesting a state of immunosuppression that extends to bystander-antigens." (PMID 38771861, 2024). "Injection drug use can contribute to simultaneous co-infection, such as HIV/hepatitis, HIV/tuberculosis, or a combination, which also affects disease progression and causes a decrease in the CD4 lymphocyte levels." (PMID 39599831, 2024). "Patients without tuberculosis showed a potentially high risk of dying compared to those with tuberculosis, whilst those with tuberculosis had a lower risk in the CD4 count recovered group." (PMID 39058196, 2024). "As described in reports in the literature, a significant drop in CD4 cells in the blood and alveolus is an important contributor to the increased risk of developing active tuberculosis." (PMID 38675837, 2024). "Age, gender, marital status, WHO clinical stage, tuberculosis (TB) status, CD4 count, risk categories, cryptococcal antigen (CRAG) status, nutritional status and weight categories were described and analysed for crude association with AHD." (PMID 39513741, 2024).
tuberculosis (continued). "This study shows an opportunistic infection, weight, and serum hemoglobin concentration were significantly associated with the log CD4 cell count and tuberculosis status of patients." (PMID 38974259, 2023). "Our findings demonstrate a correlation between the genotype and the rate of CD4+ cell count decline, which increases the risk of developing coexisting diseases beyond tuberculosis." (PMID 37606452, 2023). "The highest risk of death resulting from pneumonia and tuberculosis was observed in men, inpatients with VL ≥ 1000 copies/mL, and CD4+ counts < 350 cells/mL." (PMID 37153012, 2023). "Only three studies out of ten reported that a low CD4 level (< 200 cells/mm3) significantly increased the risk of tuberculosis in HIV-infected persons." (PMID 37723415, 2023). "The main objective was to identifying the associated factors with tuberculosis and CD4 cell count of patients in Gonder teaching referral hospital, Gonder, Ethiopia." (PMID 38974259, 2023). "HIV patients are susceptible to TB as the virus hampers the function of CD4 T cells which contributes significantly to the immune defenses against tuberculosis." (PMID 35242137, 2022). "Calcitriol supplementation can elevate CD4+ T cell levels, shorten the time to sputum culture conversion, and accelerate lesion absorption in patients with tuberculosis and 25(OH)D deficiency." (PMID 35513795, 2022). "Contact with tuberculosis-infected patients, weight loss, pneumonia on radiological examination, and low CD4+ levels were all found to be linked with M. tuberculosis." (PMID 35913968, 2022). "In this cohort study, we obtained biobanked blood samples from a large and well characterised cohort of adult patients admitted to hospital in Western Cape, South Africa with suspected HIV-associated tuberculosis and a CD4 count less than 350 cells per μL." (PMID 35644157, 2022). "Targeted transcriptional profiling of mycolipid-specific T cells from individuals with active tuberculosis reveals canonical markers associated with cytotoxicity among CD8+ compared to CD4+ T cells." (PMID 35013257, 2022). "The human immune deficiency virus (HIV) is the strongest risk factor for latent (PTB) or new infection of tuberculosis (TB) through reduction of CD4 T-lymphocytes and cellular immune function." (PMID 35132323, 2022). "A recent prognostic model for HIV-associated tuberculosis found CD4 count and antiretroviral therapy (ART) status to be important predictors of patient outcomes." (PMID 33644813, 2021). "Low CD4 counts predispose HIV-infected individuals to opportunistic infections such as tuberculosis, and HIV-associated malignancies such as KS." (PMID 34214127, 2021). "As with other intracellular pathogens, protective immune responses against tuberculosis (TB) are associated with interferon gamma (IFN-γ) production derived from T helper 1 (TH1) CD4 T cells." (PMID 34336973, 2021). "Infection by the human immune deficiency virus (HIV) is the strongest risk factor for latent or new infection of tuberculosis (TB) through reduction of CD4 T-lymphocytes and cellular immune function." (PMID 34812290, 2021). "In patients with AIDS, tuberculosis (TB) can thrive because their immune system is impaired by CD4+ T cell loss, which secondarily affects many other immune compartments (reviewed in reference 2)." (PMID 33952660, 2021). "The regression model retained greater weight, tuberculosis and a low nadir CD4 T-cell count independently associated with HIV-SN (model p = 0.0007; pseudo R2 = 0.18)." (PMID 31936167, 2020). "Another marker, PSME4, has been associated with tuberculosis through in vitro and in vivo cultures, and is also related to CD4, IFNβ1, and TGFBI pathways." (PMID 33552042, 2020). "The updated 2018 guideline widens the recommendation to include all those from high and medium tuberculosis incidence countries and those from low incidence countries with additional risk factors or low CD4+ cell count." (PMID 32501837, 2020).